NAT16 (N-acetyltransferase 16 (putative))
Description:
Probable N-acetyltransferase. Shows only trace activity toward L-His and no N-acetyltransferase activity toward other amino acids. The physiological substrate of this enzyme is unknown.
Synonyms: C7orf52; FLJ39237
Tractability: No criterion of Open Targets' tractability assessment is met for any kind of drug.
Gene: Protein-coding gene on chromosome 7 (101,170,496 to 101,180,293, reverse strand). Ensembl gene ENSG00000167011.
Subcellular location (Human Protein Atlas): Nucleoplasm
Gene Ontology:
Molecular function: acyltransferase activity, transferring groups other than amino-acyl groups
Genetic constraint (gnomAD): Loss-of-function variants: 21 observed, 16.72 expected, observed/expected ratio (o/e) 1.26, 90% interval 0.89 to 1.77. The upper end of that interval is the gene's LOEUF score, 1.77, which puts it in group 6 of 6, group 1 being the genes least tolerant of losing a copy. Missense variants: 572 observed, 491.36 expected, observed/expected ratio (o/e) 1.16, 90% interval 1.09 to 1.25. Synonymous variants: 260 observed, 225.99 expected, observed/expected ratio (o/e) 1.15, 90% interval 1.04 to 1.27.
Homologues: Orthologues: chimpanzee NAT16 (99% identical), macaque NAT16 (98% identical), tropical clawed frog nat16 (50% identical), zebrafish nat16 (49% identical), zebrafish nat16l (34% identical).
Diseases named in the same sentence as NAT16 in open-access papers:
NAT16 is named in the same sentence as 5 diseases in open-access papers, as found by Europe PMC text mining. Sharing a sentence is not in itself a finding about the gene and the disease. The quoted sentences say what the papers report.
type 1 diabetes (1 paper, 2024). "No replication was observed in the gene-aggregate tests, but NAT16 rs34985488 was replicated in the FinnGen GWAS for the CKD phenotype (p=0.0028; Bonferroni significant) and LTA rs2229092 was replicated for the type 1 diabetes with kidney complications phenotype (p=0.0044)." (PMID 39103720, 2024).
NAT16 also shares sentences with these, for which no sentence is quoted: cancer (1 paper); gastric cancer (1); kidney damage (1); kidney disease (1).